SSB (small RNA binding exonuclease protection factor La)
Diseases named in the same sentence as SSB in open-access papers (continued):
Sharing a sentence is not in itself a finding about the gene and the disease.
xerostomia (21 papers, 2008 to 2025). Dryness of the mouth resulting from reduced salivary secretion. "Circulating IL22 was significantly elevated in pSS and showed significant correlations with major characteristics such as xerostomia, anti-SSB, rheumatoid factor, and hypergammaglobulinemia." (PMID 26436101, 2015). "sB7‐H1 exhibited an increasing trend in patients with clinical symptoms such as xerostomia, xerophthalmia, decayed tooth, fatigue, arthralgia, and glandular swelling, as well as in those with high IgG levels and positivity for anti‐SSB/La, anti‐SSA/Ro60, and anti‐SSA/Ro52." (PMID 40844039, 2025). "Furthermore, we recommend assessment of autoantibodies directed against Ro/SSA and La/SSB autoantigens as soon as patients present with sicca symptoms (dry eyes and dry mouth)." (PMID 29794789, 2018). "All patients show xerophthalmia (dry eyes) and xerostomia (dry mouth) along with positivity of anti-Ro/SSA and anti-La/SSB antibodies." (PMID 39493762, 2024). "In 1997 primary SS was diagnosed based on subjective and objective dry mouth and dry eye manifestations, positive anti-Ro/SSA and anti-La/SSB antibodies and minor salivary gland biopsy showing grade 4 on Chisholm and Mason score." (PMID 19088870, 2008). "As expected there was a significant relationship between mouth opening and mRSS with anti-Scl70 antibody status (B = −0.421, p < 0.05/B = 4.560, p < 0.01; data not shown) and xerostomia with SSA/SSB antibody status (B = 2.30, p < 0.05)." (PMID 38874787, 2024). "In 2002, the American-European Consensus Group (AECG) proposed a set of classification criteria for pSS, that includes dry mouth, dry eyes, reduced salivary secretion, reduced lacrimal secretion, presence of Ro/SSA and/or La/SSB autoantibodies, and lymphocyte infiltration in minor salivary glands." (PMID 31211815, 2019). "For example, patients with sicca symptoms (dry eyes, dry mouth) lacking antibodies against Ro/SSA and La/SSB antigens are considered seronegative." (PMID 37941855, 2023).
lymphoma (15 papers, 2008 to 2025). A malignant (clonal) proliferation of B- lymphocytes or T- lymphocytes which involves the lymph nodes, bone marrow and/or extranodal sites. "They produce autoantibodies such as anti-Ro/SSA and anti-La/SSB, resulting in loss of glandular function and increased risk of lymphoma." (PMID 34281285, 2021). "Regarding anti-La/SSB positivity, it has been proposed that this variable increases the risk of lymphoma, and its increased prevalence in males further supports our finding for an association between male gender and lymphoma development." (PMID 32806710, 2020). "HCP5 rs3099844 was associated with anti-SSA (P = 0.006, OR = 3.07) and anti-SSB (P = 0.005, OR = 2.66) antibodies, severity of focus score (P = 0.03, OR = 12), and lymphoma development (P = 0.002, OR = 7.23)." (PMID 30882006, 2019). "These GC-like structures in target organs are related to the production of autoantibodies (anti-Ro/SSA and anti-La/SSB), loss of gland function, and an elevated risk of lymphoma." (PMID 31164166, 2019). "Male patients have a higher frequency of lymphoma and an increased prevalence of serum anti-La/SSB antibodies when compared to females." (PMID 37048669, 2023). "Males had a higher frequency of lymphoma compared to females (18% vs. 5.2%, OR = 3.89, 95% CI: 1.66 to 8.67; p = 0.0014) and an increased prevalence of serum anti-La/SSB antibodies (50% vs. 34%, OR = 1.953, 95% CI: 1.19 to 3.25; p = 0.0128)." (PMID 32806710, 2020). "One of these patients had a complex phenotype with high titers of anti-SSA and anti-SSB and subsequent mucosa-associated lymphatic tissue (MALT) lymphoma." (PMID 29268795, 2017). "Independent predictors for lymphoma development include salivary gland enlargement, lymphadenopathy, Raynaud phenomenon, anti-Ro/SSA or/and anti-La/SSB autoantibodies, rheumatoid factor (RF) positivity, monoclonal gammopathy, and C4 hypocomplementemia." (PMID 40978495, 2025). "However, patients with lymphoma are positive for ANA, anti-SSA, and anti-SSB antibodies." (PMID 39338221, 2024). "The absence of anti-SSA or anti-SSB antibodies in one-third of PSS patients and the inadequacy of markers predicting lymphoma highlight the necessity of investigating new autoantibodies that can be used in diagnosing PSS and predicting lymphoma development." (PMID 38310415, 2023).
congenital heart block (14 papers, 2012 to 2025). Heart block that occurs on or before 28 days of life. "The association of maternal anti-Ro/SSA and anti-La/SSB autoantibodies with congenital heart block and neonatal lupus is well known." (PMID 40117034, 2025). "Fetal exposure to anti-SSA/Ro and anti-SSB/La antibodies is associated with the development of congenital heart block (CHB)." (PMID 23320018, 2012). "It is highly recommended that patients who tested positive for anti-Ro/SSA and/or anti-La/SSB antibodies undergo vigilant screening for congenital heart block." (PMID 38895665, 2024). "Out of the 37 patients who were tested for the auto-antibodies anti-Ro/SSA and anti-La/SSB, 3 were positive, and they were closely monitored for congenital heart block throughout the pregnancy, with only one pregnancy presenting a spontaneous abortion." (PMID 36836715, 2023). "Infants and children with congenital heart block, born from anti-SSA/SSB antibodies positive mothers with SLE or pSS, are at risk of developing endocardial fibroelastosis (EFE), despite adequate pacing." (PMID 35757738, 2022). "Another example is neonatal lupus erythematosus (a disorder accompanied by congenital heart block), caused by placental transfer of anti-Ro/SSA and anti-La/SSB antibodies." (PMID 36364955, 2022). "Approximately 2% of pregnant women positive for anti-Ro/SSA and anti-SSB antibodies may experience immune-mediated fetal congenital heart block (CHB)." (PMID 41451211, 2025). "Pregnant women positive for anti-Ro/SSA and SSB antibodies may develop fetal congenital heart block (CHB)." (PMID 41451211, 2025). "Additionally, there’s potential evidence for reducing the incidence of congenital heart block among at-risk fetuses from mothers with anti-Ro/SSA and anti-La/SSB antibodies when exposed to HCQ." (PMID 38895665, 2024). "Meyer also reports that congenital heart block is rare and is present in only 1% of neonates of pregnant women with anti-Ro/SSA or anti-La/SSB autoantibodies." (PMID 26090485, 2015). "A maternal screen for congenital heart block was also negative, with normal anti-Ro/SSA and anti-La/SSB antibody levels." (PMID 41585809, 2025). "Approximately 85% of foetus with congenital heart block and absence of structural abnormalities have maternal transfer of antibodies against SSA/Ro and SSB/La; however only 2% of seropositive mother have newborns with congenital heart block." (PMID 24286473, 2013).
leukopenia (14 papers, 2015 to 2025). "In SLE patients, the GG genotype showed a protective effect with respect to develop neuropsychiatric symptoms (P = 0.037, OR = 0.24), leukopenia (P = 0.024, OR = 0.49), and nephritis (P = 0.032, OR = 0.042) but also a higher predisposition to produce anti-SSB autoantibodies (P = 0.027, OR = 2.41)." (PMID 34977255, 2021). "Accordingly, pSS patients with leukopenia have been shown to display a 6-fold higher risk of angina, while concomitant anti-Ro/SSA and anti-La/SSB positivity has been associated with a higher rate of cerebral infarction in pSS patients." (PMID 37759784, 2023). "Other highlighted risk factors are splenomegaly, lymphadenopathy, leukopenia, anti-Ro/SSA or/and anti-La/SSB positivity, monoclonal gammopathy, increased B2-microglobulin levels and increased free light chain k/l ratio." (PMID 33799655, 2021). "In the cited articles, however, in contrast to us, in the group of patients with higher IFN expression in laboratory tests, higher ANA titers, more frequent presence of anti-SSA/SSB antibodies, higher IgA concentrations, and leukopenia were noted." (PMID 35011744, 2021). "A previous study reported a close association between leukopenia and positive autoantibodies (mainly anti-SSA and anti-SSB antibodies)." (PMID 26445266, 2015). "Indeed, a peculiar poorer immunologic profile, with lower frequency of anti-SSA/SSB antibodies, leukopenia and hypergammaglobulinaemia, seems to identify patients with higher number of traditional CV risk factors, such as hypercholesterolemia." (PMID 31110500, 2019). "Laboratory tests showed liver enzyme elevation, leukopenia, hyperferritinemia, and positive anti-SSA/SSB antibodies." (PMID 40821324, 2025).
Thrombocytopenia (14 papers, 2014 to 2025). A reduction in the number of circulating thrombocytes. "Anti-SSB (P = 0.010) and RF (P = 0.004) positivity were independent potential protective factors against thrombocytopenia in patients with C-pSS." (PMID 36683822, 2022). "Multiple regression analysis showed that the expressions of anti-SSB and positive RF were independent protective factors for thrombocytopenia in C-pSS patients (OR = 0.028, 95%CI 0.002–0.427, P = 0.010; OR = 0.020, 95%CI 0.001–0.291, P = 0.004, respectively)." (PMID 36683822, 2022). "In the thrombocytopenia group, parotitis (P = 0.044), organ involvement except for hematology (P = 0.002), positive anti-SSB (P = 0.004), and positive RF (P = 0.001) were less frequently observed." (PMID 36683822, 2022). "Prevalence of anemia, thrombocytopenia and anti-SSB was significantly higher in pSS patients with anti-MDM2 autoantibody." (PMID 28147328, 2017). "Prevalence of anemia, thrombocytopenia and anti-SSB were significantly higher in pSS patients with anti-MDM2 autoantibody." (PMID 28147328, 2017). "The circulating CD4+CD161+ T cell levels were positively correlated with ESR, thrombocytopenia, and anti-SSB in pSS." (PMID 26436101, 2015). "Positive anti-SSB and positive RF values may be independent potential protective factors of thrombocytopenia in patients with C-pSS." (PMID 36683822, 2022). "Moreover, positive anti-SSB and RF may be independent potential protective factors for thrombocytopenia in pSS." (PMID 36683822, 2022). "Laboratory investigations revealed severe hyponatremia, renal impairment, anemia, thrombocytopenia, low complement levels, ANA, anti-dsDNA, anti-Sm, anti-Ro/SSA, and anti-La/SSB antibodies, and all had strongly positive serology." (PMID 41322783, 2025). "However, it is worth noting that the C4 level was lower in patients with negative SSB values and thrombocytopenia, while patients with negative anti-SSB were more likely to develop thrombocytopenia, suggesting a possible but unclear relationship between anti-SSB, C4, and thrombocytopenia." (PMID 36683822, 2022).
myositis (13 papers, 2010 to 2025). "Myositis-associated antibodies (MAA), excluding anti-SSA/SSB antibodies, were found in only two cases (5.9%) of SjS-ILD, while in the ASyS-ILD cohort, more than half of patients were positive (54.1%; p < 0.001)." (PMID 41303880, 2025). "The presence of anti-Ro/SSA, anti-La/SSB, anti-Sm, or anti-ribonucleoprotein (RNP) antibodies in a patient with myositis suggests an association or overlap with another SARD." (PMID 36899995, 2023). "Only age, gender, and the anti-SSB positive rate of pSS patients and the positivity rate of myositis-specific antibodies (MSAs) in PM/DM patients were statistically different between the different ILD scores, with p-values of 0.011, 0.007, 0.017, and 0.041." (PMID 36189284, 2022). "In 60–90% of patients with jDM, myositis-specific antibodies, such as anti-TIF 1-γ (p155), anti-NXP2/(p140/MJ), anti-MDA5, as well as myositis-associated antibodies, such as anti-La (‘SSB’), anti-Ro (‘SSA’), and anti-Sm, can be detected and helpful in establishing the diagnosis." (PMID 37726751, 2023). "Anti-Ro52 antibodies are common in patients with antisynthetase antibodies, and anti-Ro60 and anti-La/SSB may be seen with other myositis-specific antibodies." (PMID 36899995, 2023). "Other tests more commonly include myositis-specific antibodies such as anti-Jo-1, anti-Ro/SSA, anti-La/SSB, anti-smooth muscle, anti-ribonucleoprotein (RNP), anti-PM-Scl, and anti-Ku antibodies." (PMID 40161161, 2025). "All performed autoantibody tests for autoimmune rheumatic disorders, including myositis-specific antibodies (anti-Jo-1), as well as myositis-associated antibodies (anti-U1-RNP, anti-Ro52, anti-SSB and anti-PM-Scl) were negative." (PMID 41199303, 2025).
rheumatoid arthritis (11 papers, 2013 to 2025). A chronic, systemic autoimmune disorder characterized by inflammation in the synovial membranes and articular surfaces. "Anti-SSA/Ro and anti-SSB/La antibodies are autoantibodies elevated in sera of patients with systemic autoimmune diseases such as rheumatoid arthritis, lupus, and SS." (PMID 30347705, 2018).
anemia (9 papers, 2012 to 2025). A reduction in the number of red blood cells, the amount of hemoglobin, and/or the volume of packed red blood cells. "Laboratory investigation revealed mild anemia, elevated inflammatory markers, a positive ANA with speckled pattern, a positive anti-Ro/SSA, anti-La/SSB antibodies, and a positive rheumatoid factor (RF)." (PMID 33029442, 2020).
lupus nephritis (9 papers, 2015 to 2026). Glomerulonephritis in the context of systemic lupus erythematosus. "It was found that disease activity, lupus nephritis, anti SSB and hypocomplementemia were associated with ANOs, while unplanned pregnancy, lupus nephritis, new onset SLE and active disease were associated with AMOs." (PMID 39039448, 2024). "Univariate analysis revealed that the presence of lupus nephritis, active disease, positive anti-SSB, and hypocomplementemia in early pregnancy were associated with ANOs (P < 0.05)." (PMID 39039448, 2024). "Univariate analysis showed that disease activity index (P < 0.0001), lupus nephritis (P = 0.0195), anti-SSB positivity (P = 0.0074) and hypocomplementemia (P = 0.0466) were related to ANOs." (PMID 39039448, 2024). "These autoreactive responses commonly target nuclear antigens such as Ro/SSA, La/SSB, Sm, RNP, and dsDNA, the latter two specificities associated with lupus nephritis." (PMID 33613527, 2020). "Our study found a correlation between SLE disease activity, lupus nephritis, anti-SSB as well as hypocomplementemia and ANOs, suggesting that patients with these risk factors should be given more attention and intensive treatment under multidisciplinary management during pregnancy." (PMID 39039448, 2024). "Except anti-dsDNA, autoantibodies against Sm, SSA and SSB, C1q, and C-reactive protein (CRP) have been described in glomerular immune deposits in lupus nephritis patients." (PMID 31783909, 2019). "On the other hand, data from the literature suggest an association between different autoantibodies and specific clinical manifestations such as anti-dsDNA and lupus nephritis, anti-SSA/SSB and sicca symptoms, and anti-RNP and Raynaud's phenomenon." (PMID 26063969, 2015). "Patients with LM had a higher incidence of lupus nephritis and a higher positivity rate for anti-SSB antibodies than those with SLE without LM." (PMID 41978272, 2026).
scleroderma (8 papers, 2008 to 2025). Scleroderma is a rare autoimmune connective tissue disorder characterized by abnormal hardening of the skin and, sometimes, other organs. "Autoantibodies in saliva were grouped into autoantibody Sa-C-1 (anti-RNP, anti-insulin, anti-mitochondrial, SSB and anti-scleroderma-70 antibodies) and autoantibody Sa-C-2 (anti-β2 glycoprotein)." (PMID 18289371, 2008).
sialadenitis (8 papers, 2017 to 2025). Sialadenitis is an infection of the salivary glands. "An early study demonstrated that murine cytomegalovirus induced an SjD-like disease in C57Bl/6-lpr/lpr mice with sialadenitis, severe SG inflammation, and production of anti-SSA/Ro and anti-SSB/La." (PMID 37676726, 2023). "–10 Along with dry eye and dry mouth, other hallmarks of SS include the presence of lymphocytes within lacrimal (i.e., dacryoadenitis) and salivary (i.e., sialadenitis) glands, as well as the serum autoantibodies, anti-SSA/Ro and anti-SSB/La." (PMID 35727180, 2022). "The SS phenotype in TLR8ko mice is manifested by sialadenitis, increased anti-SSA and anti-SSB autoantibody production, immune complex deposition and increased cytokine production in salivary glands, as well as lung inflammation." (PMID 34108972, 2021). "Here we show that TLR8ko mice also develop SS that is characterized by sialadenitis, lung inflammation, increased SSA and SSB autoantibody production, and within the SG deposition of IgG and IgM immune complex, increased cytokine and chemokine production and presence of ELS." (PMID 34108972, 2021). "However, as the Copenhagen criteria were used, in which the presence of anti-SSA/SSB or presence of focal sialadenitis are not mandatory, several patients not fulfilling the AECG criteria were included in that study." (PMID 28270185, 2017).
vasculitis (8 papers, 2007 to 2024). "The incidence of vasculitis in patients with pSS is thought to be secondary to complement activation by the anti-SSA/SSB antibodies and occurs in around 9% of cases." (PMID 36253840, 2022). "Risk factors potentially associated with increased mortality were older age at diagnosis, male gender, parotid enlargement, abnormal parotid scintigraphy, extra-glandular involvement, vasculitis, anti-SSB positivity, hypocomplementemia and cryoglobulinemia." (PMID 34100160, 2022). "Patients with vasculitis have a higher prevalence of anti-Ro/SSA and/or anti-La/SSB antibodies, and about one-third of them have positive cryoglobulins." (PMID 37373950, 2023). "Laboratory testing for diabetes, vasculitis, and anti-double-stranded DNA, anti-Ro/SSA, anti-La/SSB, anti-nuclear antibodies, and anti-neuronal antibodies were negative." (PMID 35283724, 2022).
Arthritis (7 papers, 2013 to 2026). Inflammation of a joint. "Comparatively, anti-SSB/La, tender joint count, swollen joint count, IgG, symmetric arthritis, ESR, and IgA exhibited relatively limited influence in distinguishing between the two disease categories." (PMID 40698089, 2025). "Arthritis, fever, serositis, Raynaud's syndrome, lung disease, neuropsychiatric symptoms, positive antinuclear antibody tests, positive rheumatoid factor, positive anti-Ro/Sjögren's syndrome (SS) A, and positive anti-La/SSB are more common in patients with elderly-onset lupus." (PMID 25374741, 2013). "It correlates with distinct clinical (rash, alopecia, arthritis, Raynaud syndrome) and immunological (anti-Sm/SSA/SSB antibodies, decreased C3/C4, RF positivity) features." (PMID 41495809, 2026). "Compared with OA patients in this cohort, we saw that arthritis patients showed positive results of eye desiccation examination and salivary gland ECT, as well as higher positive rates of anti-SSA, anti-SSB, CCP antibody, and RF." (PMID 36647153, 2023).
lymphopenia (7 papers, 2020 to 2025). Reduction in the number of lymphocytes. "The laboratory results indicated lymphopenia and normocytic normochromic anemia as well as hypergammaglobulinemia, positive antinuclear antibodies and high titers of anti-Ro/SSA (>200 UI/L) and anti-La/SSB antibodies (>200 UI/L)." (PMID 32674462, 2020).
Lymphadenopathy (6 papers, 2018 to 2025). Enlargement (swelling) of a lymph node. "In the same study, when triple autoantibody negative (ANA positive, but antiSSA/Ro, SSB/La, and RF negative) patients were compared with quadruple autoantibody negative patients, the frequency of lymphadenopathy and lymphoma was found to be lower in the quadruple autoantibody negative group." (PMID 39473752, 2024).